IL6 (interleukin 6)
Diseases named in the same sentence as IL6 in open-access papers (continued):
Sharing a sentence is not in itself a finding about the gene and the disease.
autoimmune disease (continued). "Molecular-targeted drugs used in RA treatment, which target tumor necrosis factor, interleukin 6 (IL-6), etc., were expanded to many other autoimmune diseases." (PMID 37371540, 2023). "IL-6 is involved in uncontrolled inflammation during autoimmune diseases and chronic inflammatory diseases." (PMID 37397366, 2023). "On the other hand, aconite can inhibit the release of inflammatory cytokines, including IL-6, IL-8, and IL-10, in several autoimmune diseases." (PMID 36756040, 2023). "Inhibition of signaling mechanism of IL-6 with JAK/STAT inhibitors proved efficient in autoimmune disease." (PMID 36839968, 2023). "In this context, interleukin induction properties of mimic peptides were assessed using available web servers for IL-4, IL-6, and IL-13, as interleukins are involved in autoimmune disorders." (PMID 37513704, 2023). "Generally, as a pleiotropic cytokine, IL-6 plays a central role in human physiological and pathophysiological responses, such as participating in inflammation, autoimmune diseases, and cancer." (PMID 37781036, 2023). "Key cytokines like IL-6 and IL-1β emerge as central players in these changes, with potential implications for tissue repair and autoimmune disease exacerbation." (PMID 38090572, 2023). "IL-6 is the main indicator of inflammation for chronic inflammatory diseases (including autoimmune diseases, cancers and cytokine storms), which supports the data showing its involvement in CSU pathogenesis." (PMID 37626727, 2023). "Th17 cells were demonstrated to secrete IL-6 and IL-17, which play a part in inflammatory and autoimmune diseases." (PMID 37373070, 2023). "Meanwhile, ARID5A has been shown to mainly regulate inflammatory and autoimmune disease development by regulating the expression of Interleukin-6 (IL-6) mRNA." (PMID 36755810, 2023). "Interleukin-6 dysregulation is noted in many autoimmune diseases, and treatments targeting the interleukin-6 pathway, such as tocilizumab, have been approved for RA and other autoimmune diseases." (PMID 38137680, 2023). "The IL6ST gene is near ANKRD55, and IL-6 is more attractive for its precise role in inflammation and autoimmune disease." (PMID 35983018, 2022). "In this study, we revealed an immunomodulatory role of lantibiotic peptides salivaricins in autoimmune disease, demonstrating that salivaricins beneficially modulate host immunity by directly binding to and inhibiting IL‐6 and IL‐21 receptors." (PMID 36031409, 2022). "Blocking IL-6 by means of an antibody against its receptor has proven to be efficacious in various autoimmune diseases." (PMID 36524015, 2022). "Inflammatory fibroblasts are a major source of pro‐inflammatory cytokines such as IL6.[22b] IL6 has been repeatedly linked to IC/BPS, and blockade of IL6 has been shown to alleviate inflammation in preclinical studies of other autoimmune diseases." (PMID 35470584, 2022). "Immune blockade of IL-6 is approved for use in autoimmune diseases with a substantial role in inflammation; a few anti-IL-6 therapies are currently in use for rheumatologic disease, yet there is a lack of studies in heart failure." (PMID 36672578, 2022). "Many chronic diseases, such as cardiovascular diseases, cancer, and autoimmune diseases, are related to increased levels of inflammatory factors such as IL-1β, IL-6, tumor necrosis factor (TNF), and C-reactive protein (CPR)." (PMID 36062133, 2022). "Interleukin-6 (IL-6) is a multi-faceted cytokine that mediates responses to trauma, infection, autoimmune diseases and is involved in the development of neoplastic diseases." (PMID 35884907, 2022). "Our findings highlight several key aspects of the IL-6 pathway on the promotion of human T cell phenotypes with implications for autoimmune diseases." (PMID 35911690, 2022). "And there is evidence that IL-6 can induce and magnify the production of autoantibodies in autoimmune diseases." (PMID 35979351, 2022).
autoimmune disease (continued). "TNF-α and IL-6 were first discussed in large samples of different autoimmune diseases to evaluate the potential of them as disease markers." (PMID 35911746, 2022). "IL-6, a cytokine secreted by macrophages, monocytes, and T cells after these cells are activated under inflammation, plays an important role in autoimmune diseases and infection." (PMID 35453256, 2022). "Collectively, these findings should be taken into account as we consider the role of IL-6 in disease pathogenesis and translating IL-6 biology into effective therapies for T cell-mediated autoimmune disease." (PMID 35911690, 2022). "The pro-inflammatory characteristic also represents IL-6, a cytokine involved in immune responses, hematopoiesis, bone metabolism, the development of autoimmune diseases, bacterial infections, and metabolic side effects." (PMID 36357780, 2022). "IL-6 is one of the main cytokines that at high levels can promote inflammatory processes and is involved in the pathogenesis of several autoimmune diseases, including neuromyelitis optica spectrum disorder (NMOSD)." (PMID 35043373, 2022). "Despite these somewhat paradoxical observations, the pursuit of anti‐IL‐6 therapies in inflammatory myopathies (and wider autoimmune diseases) is highly prevalent." (PMID 36426551, 2022). "As an early discovered cytokine, IL6 plays a vital role in chronic inflammation, autoimmune diseases, cancers, and cytokine storms." (PMID 35692503, 2022). "TNF-α is considered to be an important pro-inflammatory cytokine in T cell-mediated autoimmune diseases, and its biological effects in MG include induction of IL-6, activation of B cells, and priming of AChR-specific T cells." (PMID 36303555, 2022). "The blocking of IL-6 by means of an antibody against its receptor has proven to be efficacious in various autoimmune diseases." (PMID 36524015, 2022). "The engagement of IL-6 in IBD and colorectal cancer pathogenesis has been well explored, and some anti-IL-6 mAbs have been tested in RCTs against autoimmune diseases." (PMID 36145301, 2022). "Deregulated continual synthesis of IL-6 has pathological effects on inflammatory and autoimmune diseases." (PMID 35432339, 2022). "Psoriasis is an autoimmune disease with modest systemic aberrations of IL-6, CRP, TNF-α, E-selection, and ICAM and comorbidity with SCZ." (PMID 35082268, 2022). "Accordingly, an imbalance between pro-inflammatory cytokine-producing B cells (mainly B cells producing IL-6) and IL-10-producing B cells has been described in multiple autoimmune diseases." (PMID 36179248, 2022). "We found that POTS patients had elevations of the proinflammatory cytokines IL-1β, IL-6, IL-18, and INFΥ, which have been reported in both autoinflammatory and autoimmune diseases and, potentially, are a result of abnormal NK cell function." (PMID 35269395, 2022). "T1DM is an autoimmune disease in which pancreatic β cells are destroyed by infiltrating macrophages and by T cells that secrete IL-6, TNF-α, and interferons." (PMID 35669071, 2022). "Pro-inflammatory cytokine IL-6 is instrumental in chronic inflammatory diseases and autoimmune diseases, as well as bone metabolism, and predominantly exerts its effect through the IL-6-signal transducer and activator of transcription 3 (STAT3) pathway." (PMID 36417596, 2022). "Innate immune activation is a common denominator in the pathophysiology of autoimmune diseases, and is many times characterized by increases in immune mediators, such as cytokines like TNFα and IL6, and exaggerated inflammasome activity." (PMID 35246034, 2022). "On the other hand, the continuous synthesis of IL-6 has deleterious consequences, contributing to the development of inflammatory and autoimmune diseases." (PMID 35888173, 2022). "Th17 cells, a subset of CD4+T lymphocytes, produce inflammatory cytokines such as IL-6 and IL-17, which promote the body’s inflammatory response and are the main participants in autoimmune diseases." (PMID 36524110, 2022).
autoimmune disease (continued). "Increased levels of IL-6 are observed in patients with cancer or autoimmune diseases, and also in cancer patients who develop immune toxicity from immunotherapy, chimeric antigen receptor-T (CAR-T) therapy, or ICI." (PMID 36081549, 2022). "On the other hand, excessive IL-6 secretion induces chronic inflammatory diseases, autoimmune diseases, cancer, and cytokine storms." (PMID 36012469, 2022). "The JAK inhibitor tofacitinib and IL-6 inhibitor sarilumab have been used for the treatment of various autoimmune diseases, such as RA." (PMID 36439145, 2022). "This suggests that KD exhibits a similar phenotype with autoimmune diseases, characterized by immune system activation of signaling pathways related to IL-1, IL-6, and TNF and the involvement of T/B cells." (PMID 36042431, 2022). "Since IL-6 is a mediator of fever and acute-phase responses, the blockade of IL-6/IL-6R alleviates the symptoms in autoimmune diseases." (PMID 35655291, 2022). "CEBPD is a transcription factor that forms a heterodimer with CEBPB (PPi score = 0.991), which further regulates the transcription of IL-6, a key proinflammatory cytokine overexpressed in multiple autoimmune diseases." (PMID 35627163, 2022). "Resistance to Treg-mediated suppression has been reported for effector TH cells in autoimmune disease like multiple sclerosis and type 1 diabetes, and was reported to involve granzyme B and IL-6." (PMID 34073458, 2021). "Our study evaluated the relation between sialoglyco-conjugate abnormalities, gangliosides and IL-6 in SLE and LN, and also, glycosphingolipids alteration influence on IL-6 signaling in these autoimmune disease." (PMID 34205600, 2021). "IL-6 is used to predict and evaluate inflammation levels in patients with cancer, infection, autoimmune diseases, pancreatic diseases, and cardiovascular diseases." (PMID 34946724, 2021). "Elevated levels of IL-6 have been detected in the blood of patients with microbial infections, autoimmune diseases, neoplasia, and muscular dystrophy." (PMID 34359985, 2021). "Previous studies have shown that IL-6 is an important regulatory factor in the development of autoimmune diseases." (PMID 34539800, 2021). "The fostering of this medication was based on the pathologic role exerted by Il-6 and the massive and unregulated expression and production of Il-6 in patients with autoimmune diseases such as RA and Still’s disease." (PMID 34458951, 2021). "The IL-6 -174G/C polymorphism that we have studied in CTCL has already been proved to be related to inflammatory and autoimmune diseases." (PMID 32270320, 2021). "Numerous data indicate that the dysregulation of IL-6 expression is the main factor in the pathogenesis of chronic inflammatory and autoimmune diseases." (PMID 34835417, 2021). "In this regard, dysregulated and persistent IL-6 production results in severe inflammatory and autoimmune disorders." (PMID 34600590, 2021). "Interleukin 6 (IL6) is an inflammatory cytokine that is an endogenous pyrogen of inducing fever in patients with autoimmune diseases or infections." (PMID 33737684, 2021). "Several studies have identified a role for IL-6 and members of the IL-6 superfamily (IL-11, IL-23, IL-27, and IL-31) in contributing to autoimmune disorders, cancer, and GVHD." (PMID 34899738, 2021). "Inhibition of IL-6 activity by neutralizing antibodies to the IL-6R has been approved in many countries for the treatment of autoimmune diseases." (PMID 34141712, 2021). "The supporting function of the inflammatory process implemented by IL-6 can be counteracted using an opposing cytokine such as IL-4 both in the acute phase and, for example, for the contrast of the triggers of autoimmune diseases." (PMID 34067872, 2021). "IL-6 contributes to the development of autoimmune diseases by promoting the differentiation and expansion of Th17 cells and suppressing Tregs." (PMID 33816637, 2021).
autoimmune disease (continued). "IL-6 is up-regulated in inflammatory processes such as infections, trauma, autoimmune diseases, and cancer." (PMID 33461943, 2021). "However, in IL-6 cluster signaling, the IL-6/IL-6Rα complex forms internally in dendritic cells (DCs) and interacts with gp130 expressed on antigen-specific T cells, a pathway which may be relevant to multiple T lymphocyte-associated autoimmune diseases." (PMID 33816637, 2021). "The expression of IL6 increased when the host developed with infection, autoimmune disease, or cancer." (PMID 34485521, 2021). "Levels of interleukin-6 (IL-6), a proinflammatory cytokine and key factor in the pathogenesis of autoimmune diseases, have been reported to be elevated in vitiligo lesions." (PMID 33959187, 2021). "Interleukin-6 (IL-6) is a major inflammatory cytokine also involved in cancer and autoimmune diseases." (PMID 34885656, 2021). "This pool of mononuclear macrophages produces large quantities of proinflammatory cytokines such as TNF, IL-6, and 1-β, leading to autoimmune disease severity." (PMID 33946736, 2021). "Interleukin 6 is one of the major targets of therapeutic design in various autoimmune disease and infectious diseases." (PMID 35011356, 2021). "The role of IL-6 in autoimmune diseases helps to understand the mechanism of the effect of tocilizumab on B- and T-cell subsets." (PMID 34394101, 2021). "Other IL-6/IL-6R blockades that are FDA-approved or undergoing RCT for autoimmune diseases include clazakizumab, siltuximab, sarilumab, olokizumab, sirukumab, and tofacitnib." (PMID 34441950, 2021). "In recent years, remarkable advances have been made in translating the biology of IL-6 to the treatment of patients with various autoimmune diseases, including RA." (PMID 35126375, 2021). "The hyperactivation mechanism of NF-κB by STAT3 leads to the activation of the interleukin-6 amplifier (IL-6 Amp), resulting in multiple inflammatory and autoimmune diseases." (PMID 32898468, 2020). "In the context of autoimmune disease, IL-6 in combination with TGFβ1 promotes the differentiation of Th17 cells." (PMID 32934336, 2020). "SOCS3 has been reported involving in the progress of various diseases such as autoimmune diseases, cardiovascular diseases, metabolic diseases and tumours, which is responsive to an increase in IL-6 and plays a negative regulatory role in cytokine signalling." (PMID 32272865, 2020). "IL-6 stimulates the body's defense response in several situations, including infections or autoimmune diseases." (PMID 32574285, 2020). "Recent studies have found that IL-6 plays a promotive role in the occurrence and development of various autoimmune diseases." (PMID 32738911, 2020). "This is the most important role of IL-6, as it is involved in multiple autoimmune diseases and contributes directly to the survival of plasma cells in the bone marrow niche." (PMID 33240910, 2020). "As an autoimmune disease, the innate immune system is persistently activated in RA and continuously expressed cytokines such as IL-1 and IL-6." (PMID 34138288, 2020). "Biological agents targeting key pro-inflammatory cytokines, such as interleukin 6 (IL-6), have proved to be effective in the treatment of autoimmune diseases." (PMID 32781571, 2020). "To date, anti-IL-6 therapy has been widely used to treat autoimmune diseases, including rheumatic arthritis, giant cell arteritis, and adult-onset Still's disease (AOSD)." (PMID 32733444, 2020). "Recently, Th17 related cytokines such as IL-1β, IL-6, IL-17, IL-21, IL-22, and IL-23 play crucial roles in the pathogenesis of many diseases, including inflammatory diseases, autoimmune diseases, and cancers." (PMID 32252668, 2020). "Members of the IL-6/IL-12 cytokine family are critical regulators of innate and adaptive immunity and have emerged as key players controlling inflammatory and autoimmune disorders." (PMID 33259477, 2020).
autoimmune disease (continued). "This is the most important function of IL-6, since IL-6 is involved in multiple autoimmune diseases and contributes directly to the survival of plasma cells in the bone marrow niche." (PMID 33240910, 2020). "Interleukin 6 is a key regulator of immune-related reactions involved in inflammatory processes, such as autoimmune diseases or anticancer-induced cardiotoxicity." (PMID 32781690, 2020). "Because of a price gap between manufacturing costs and drug prices, the development of IL-6 mAb for autoimmune diseases was initially abandoned, and the focus was diverted toward the development of drugs for multiple myeloma instead." (PMID 32743515, 2020). "As overshooting inflammation induces pathologies such as autoimmune diseases, chronic inflammation, and even cancer, the action of interleukin-6 is rigorously controlled." (PMID 31238931, 2019). "IL-6 is a well-known cytokine and biomarker related to inflammation, autoimmune diseases and late stage cancers." (PMID 30670783, 2019). "Interleukin-6 (IL-6), a pleiotropic cytokine and major mediator of inflammation, is involved in many biological processes, including cancer and autoimmune diseases." (PMID 31817563, 2019). "Currently, similar to the C-reactive protein (CRP), IL-6 is used to “monitor” inflammation levels in patients with cancer, infection, or autoimmune diseases." (PMID 31795299, 2019). "Some of these disrupted inflammatory mediators, like CXCL11, CXCL20, IL-6, IL-1β, are involved in the pathogenesis of autoimmune disorders and play a potential role in tumor progression and metastasis." (PMID 31200452, 2019). "Despite these beneficial functions of IL-6, dysregulated IL-6-induced signalling (e.g. hyper-activation of JAK/STAT signalling) contributes to the development of pathologies such as autoimmune diseases, chronic inflammation, or even cancer." (PMID 31238931, 2019). "In patients with autoimmune diseases, increased frequencies of a heterozygous IL-6 promotor SNP rs1800795 were identified." (PMID 31366164, 2019). "Interleukin 6 (IL-6) has emerged as a major player in the pathogenesis of autoimmune disease and chronic inflammation." (PMID 31523783, 2019). "Abnormal expression of IL13 is found in many autoimmune diseases with an inflammatory response, while IL6 is released mainly by white blood cells and activates the synthesis of acute phase proteins, like CRP." (PMID 31194785, 2019). "Stringent and well controlled action of IL-6 function is crucial because malregulated IL-6 signalling contributes to inflammatory and autoimmune diseases and cancer." (PMID 31651330, 2019). "The anti-inflammatory cytokine IL-6 is increased in neuronal and CNS autoimmune diseases, such as neuromyelitis optica and multiple sclerosis." (PMID 30792710, 2019). "Conversely, states of acute inflammation mediated via IL-6, cancers and chronic and autoimmune diseases lead to an increase in hepcidin levels." (PMID 31700042, 2019). "Pro-inflammatory cytokines such as TNF-α and IL-6 play crucial roles in the development of inflammatory diseases and are involved in immunity and autoimmune diseases." (PMID 29401674, 2018). "Elevated sIL-6R by auto-reactive CD4+ T cells contributes to autoimmune disease development via conferring IL-6 responsiveness as well as blocking Treg development." (PMID 30327657, 2018). "SLE is a typical autoimmune disease involving the activation of T and B cells that, despite few previous reports, is expected to be affected by IL-6 inhibition." (PMID 30423923, 2018). "The blood levels of IL-6, a potent pro-inflammatory agent that plays a crucial role in the pathogenesis of autoimmune diseases, were much higher in arthritic mice treated with vehicle than in sham animals." (PMID 29490676, 2018). "High levels of IL-6 and sIL-6R have been demonstrated in several chronic inflammatory and autoimmune diseases, suggesting IL-6/sIL-6R complex involvement in the transition from acute to chronic inflammation." (PMID 29385088, 2018).